COL8A2 (collagen type VIII alpha 2 chain)
Description:
Macromolecular component of the subendothelium. Major component of the Descemet's membrane (basement membrane) of corneal endothelial cells. Also a component of the endothelia of blood vessels. Necessary for migration and proliferation of vascular smooth muscle cells and thus, has a potential role in the maintenance of vessel wall integrity and structure, in particular in atherogenesis (By similarity).
Synonyms: PPCD; FECD1; PPCD2; FECD
Tractability: Antibody: its Gene Ontology location is reachable by antibodies, with high confidence; UniProt places it where antibodies can reach, with medium confidence; UniProt predicts a signal peptide or a membrane-spanning region.
Gene: Protein-coding gene on chromosome 1 (36,095,239 to 36,125,222, reverse strand). Ensembl gene ENSG00000171812.
Subcellular location: Secreted, extracellular space, extracellular matrix, basement membrane
Subcellular location (Human Protein Atlas): Golgi apparatus; Predicted to be secreted
Pathways (Reactome):
Extracellular matrix organization: Assembly of collagen fibrils and other multimeric structures; Collagen biosynthesis and modifying enzymes; Collagen chain trimerization; Collagen degradation; Integrin cell surface interactions
Gene Ontology:
Molecular function: extracellular matrix structural constituent; extracellular matrix structural constituent conferring tensile strength; protein-macromolecule adaptor activity
Biological process: basement membrane assembly; cell-cell adhesion; extracellular matrix organization
Cellular component: extracellular matrix; basement membrane; collagen type VIII trimer; elastic fiber; endoplasmic reticulum lumen; extracellular region
Genetic constraint (gnomAD): Loss-of-function variants: 16 observed, 21.34 expected, observed/expected ratio (o/e) 0.75, 90% interval 0.51 to 1.14. The synonymous counts are far from expectation, so gnomAD's model fits this gene poorly and the ratio says little. Missense variants: 818 observed, 841.13 expected, observed/expected ratio (o/e) 0.97, 90% interval 0.92 to 1.03. Synonymous variants: 466 observed, 382.63 expected, observed/expected ratio (o/e) 1.22, 90% interval 1.13 to 1.32.
Homologues: Orthologues: chimpanzee COL8A2 (99% identical), macaque COL8A2 (99% identical), rabbit COL8A2 (96% identical), pig COL8A2 (96% identical), dog COL8A2 (95% identical), guinea pig COL8A2 (94% identical), mouse Col8a2 (94% identical), rat Col8a2 (92% identical), tropical clawed frog col8a2 (67% identical), zebrafish col8a2 (62% identical). Paralogues in human: COL8A1 (53% identical), COL10A1 (51% identical), COL19A1 (37% identical), OTOL1 (23% identical), C1QTNF9 (20% identical), C1QTNF9B (19% identical), C1QTNF7 (15% identical), C1QTNF2 (14% identical), C1QTNF3 (13% identical), ADIPOQ (13% identical), C1QL2 (13% identical), C1QC (13% identical), and 11 more.
Diseases named in the same sentence as COL8A2 in open-access papers:
COL8A2 is named in the same sentence as 36 diseases in open-access papers, as found by Europe PMC text mining. Sharing a sentence is not in itself a finding about the gene and the disease. The quoted sentences say what the papers report.
Fuchs endothelial corneal dystrophy (11 papers, 2010 to 2026). Fuchs endothelial corneal dystrophy (FECD) is the most frequent form of posterior corneal dystrophy (see this term) and is characterized by excrescences on a thickened Descemet membrane (corneal guttae), generalized corneal edema, with gradually decreased visual acuity. "Dysregulation of Col8a1 and Col8a2 is implicated in a broad spectrum of disorders, including vascular remodeling, tissue fibrosis, diabetic nephropathy, cancer progression, and corneal endothelial dystrophies." (PMID 41641337, 2026). "A missense mutation of the collagen 8A2 (COL8A2) gene in humans causes early-onset Fuchs’ dystrophy." (PMID 34100716, 2021). "Although other mutations within the ZEB1/TCF8 locus and TCF4 trinucleotide repeats are associated with Fuchs’ dystrophy, only the Col8a2 missense mutant mouse has successfully recapitulated its key features." (PMID 34100716, 2021). "In this review, we first summarized the mutations of COL8A2, TCF4, TCF8, SLC4A11 and AGBL1 genes in Fuchs endothelial corneal dystrophy." (PMID 34130750, 2021). "Mutations in COL8A2 gene which encodes the collagen alpha-2 (VIII) chain have been identified in both familial and sporadic cases of Fuchs endothelial corneal dystrophy (FECD)." (PMID 20144242, 2010). "The pathogenic role of variants in TCF4 and COL8A2 in causing Fuchs’ endothelial corneal dystrophy (FECD) is not controversial and has been confirmed by numerous studies." (PMID 37441688, 2023). "Similarly, variants in ZEB1, COL8A2, TCF4, FEN1, AGBL1, and LOXHD1 all cause Fuchs endothelial corneal dystrophy (FECD), while the age of onset may vary." (PMID 31555324, 2019).
glaucoma (4 papers, 2010 to 2021). Increased pressure in the eyeball due to obstruction of the outflow of aqueous humor. "COL8A2 mutations have been found in some glaucoma patients, and its expression is elevated in HTM cells in response to dexamethasone suggesting a role in GC-induced glaucoma as well as in the development of the anterior segment." (PMID 34440692, 2021). "Notably, rare COL8A2 mutations have been found in some glaucoma patients." (PMID 22312193, 2012). "Further study of COL8A2 variants in other patient populations, especially those with thinner CCT such as African-Americans would provide further support for a role of COL8A2 in corneal thickness and in glaucoma." (PMID 21139683, 2010). "Both COL8A2 and POSTN have been reported to be associated with glaucoma." (PMID 34440692, 2021). "Expressional elevation of COL8A2 (collagen, type VIII, alpha 2) in TM cells in response to dexamethasone treatment has also been observed, and it has been suggested that this is part of the pathological process leading to steroid-induced glaucoma." (PMID 22312193, 2012).
breast carcinoma (3 papers, 2016 to 2024). "Potential biomarkers for canine and human mammary carcinoma may be EMT-related genes such as COL11A1, COL8A2, and ADAM12 which are overexpressed in mammary carcinoma." (PMID 33282730, 2020).
Fuchs' endothelial dystrophy (3 papers, 2018 to 2024). Fuchs endothelial corneal dystrophy (FECD) is the most frequent form of posterior corneal dystrophy and is characterized by excrescences on a thickened Descemet membrane (corneal guttae), generalized corneal edema, with gradually decreased visual acuity. "Furthermore, COL8a1 and COL10a1 are associated with age-related macular degeneration whereas mutations in COL8a2 can lead to Fuchs endothelial dystrophy, an impairment of vision." (PMID 38997817, 2024). "Multiple genetic loci have been linked to Fuchs' endothelial dystrophy, including but not limited to TCF4, COL8A2, SLC4A11, ZEB1 and LOXHD1." (PMID 29685994, 2018).
keratoconus (3 papers, 2010 to 2023). A degenerative, structural disorder of the eye, characterized by a cone-shaped protrusion of the cornea. "Although the COL8A2 gene (OMIM: #120252) is associated with the phenotypes of FECD type 1 (MIN: #136800) and PPCD type 2 (MIM: #609140) with an autosomal dominant inheritance pattern, COL8A2 is associated with corneal thinning and keratoconus." (PMID 37895187, 2023). "COL8A2 mutations have not been found in patients with keratoconus or keratoglobus." (PMID 21139683, 2010). "Missense mutations in COL8A2 resulted in posterior polymorphous corneal dystrophy (PPCD) and FECD, although no pathologic variants have been reported in keratoconus." (PMID 36292595, 2022).
posterior polymorphous corneal dystrophy (3 papers, 2020 to 2023). Posterior polymorphous corneal dystrophy (PPCD) is a rare mild subtype of posterior corneal dystrophy characterized by small aggregates of apparent vesicles bordered by a gray haze at the level of Descemet membrane, generally with no effect on vision. "For example, mutations in the COL4A1 and COL8A2 genes have been shown to induce PA, posterior polymorphous corneal dystrophy (PPCD), or corneal endothelial dystrophy." (PMID 33304895, 2020).
corneal disease (2 papers, 2010 to 2022). "The currently available version only includes genes that underlie much rarer genetic causes of inherited corneal disease (eg, COL8A2), limiting its clinical utility." (PMID 36161831, 2022). "As the previous reports relating COL8A2 missense changes to corneal disease have not included CCT measurement as part of the clinical assessment, it is not possible to determine if the patients carrying these gene variants also had thin CCT." (PMID 21139683, 2010).
glioblastoma (2 papers, 2017 to 2023). The most malignant astrocytic tumor (WHO grade IV). "Among these, PAPPA was discovered to be a highly differentially expressed therapeutic target in Ewing sarcoma, COL8A2 is a crucial part of the basement membrane of corneal endothelial cells, and it can encourage the malignant development of glioblastoma cells by triggering EMT." (PMID 37777759, 2023). "A literature review identified DUSP4, HIF-1α, and COL8A2 as being linked to ERK signaling, and analysis of a published dataset of chromatin immunoprecipitation sequencing (ChIP-seq) data for Bmi1 in neural stem cells and glioblastoma cells identified Dusp4 as a direct Bmi1 target gene." (PMID 29212025, 2017).
atherosclerosis (1 paper, 2025). A disease characterized by the build-up of fatty material and calcium deposition in the arterial wall resulting in partial or complete occlusion of the arterial lumen. "Given the role of Collagen VIII in neovascularization and its association with atherosclerosis, altered expression of Col8a1 and Col8a2 in progenitors could represent a mechanistic target in aortic disease." (PMID 40277904, 2025).
corneal dystrophy (1 paper, 2023). The term corneal dystrophy embraces a heterogeneous group of bilateral genetically determined non-inflammatory corneal diseases that are usually restricted to the cornea. "All COL8A2-related corneal dystrophy variants to date are amino acid substitutions and pLI is low (0.12)." (PMID 37644014, 2023).
infections in the skin (1 paper, 2016). "More interesting, we found five genes (CDKN2A, COL8A2, RASSF6, TMC4, and TMC5) from our 145 genes are associated with Walt’s disease (corrected P-value = 0.0040), which are infections in the skin caused by the human papillomavirus (HPV)." (PMID 27830726, 2016).
myopia (1 paper, 2022). "Taken together, scleral Col1a1, Col4a3, Col8a2, Col11a2, and Col15a1 expression were regulated through ER stress during the myopia progression." (PMID 36216837, 2022).
osteomyelitis (1 paper, 2022). An acute or chronic inflammation of the bone and its structures due to infection with pyogenic bacteria. "Between the two gene subtypes, the expression of 3 collagen-related genes was significantly different, among which COL4A1, COL8A2 and COL18A1 were all highly expressed in gene cluster A osteomyelitis." (PMID 36544487, 2022). "Between the two m6A subtypes from the validation group, the expression of 2 collagen-related genes was significantly different, with COL8A2 and COL18A1 both highly expressed in cluster A osteomyelitis." (PMID 36544487, 2022). "Between the two gene subtypes, the expression of 2 collagen-related genes was significantly different, among which COL8A2 and COL18A1 were all highly expressed in gene cluster A osteomyelitis." (PMID 36544487, 2022).
ovarian carcinoma (1 paper, 2023). A malignant neoplasm originating from the surface ovarian epithelium. "Additionally, we explored the detailed distribution of MGP, COL8A2, and PAPPA in ovarian cancer using single-cell RNA transcriptome data (GSE147082) from the TISCH database." (PMID 37777759, 2023).
cancer (7 papers, 2020 to 2026). A tumor composed of atypical neoplastic, often pleomorphic cells that invade other tissues. "Given the role of CAFs in interacting with cancer cells via growth factors, inflammatory ligands, and ECM proteins,we investigated the correlation between MGP, COL8A2, and PAPPA with CAF markers." (PMID 37777759, 2023). "The genome-wide co-expression analyses showed that the expression levels of collagen genes (COL1A1, COL1A2, COL5A1, COL5A2, COL8A1 and COL8A2) and LincRNAs (Linc01614 and Linc01711) were significantly positively correlated with PODNL1 expressions in various cancers." (PMID 37504302, 2023).
tumor (4 papers, 2021 to 2023). "It has been demonstrated that MGP, COL8A2, and PAPPA are effective immunological checkpoints that mediate tumor immunosuppression." (PMID 37777759, 2023). "For instance, COL8A1, COL8A2, and COL21A1 were only detected in normal tissues whereas COL7A1 and MUC1 were exclusively identified in tumor samples." (PMID 34199725, 2021).
cardiovascular disease (1 paper, 2025). "Of particular relevance to PVAT remodeling during cardiovascular disease is the observed expression of Col8a1 and Col8a2 and their downregulation during adipogenesis." (PMID 40277904, 2025).
COL8A2 also shares sentences with these, for which no sentence is quoted: corneal endothelial dystrophies (3 papers); connective tissue diseases (2); Obesity (2); adenovirus infection (1); age-related macular degeneration (1); ameloblastoma (1); brittle cornea syndrome (1); diabetic nephropathy (1); endometriosis (1); Ewing sarcoma (1); Hepatic fibrosis (1); infection (1); ischemia (1); osteoarthritis (1); osteoporosis (1); primary open angle glaucoma (1); Stargardt disease (1); Stroke (1); systemic sclerosis (1).